INS (insulin)
Diseases named in the same sentence as INS in open-access papers (continued):
Sharing a sentence is not in itself a finding about the gene and the disease.
Insulin resistance (continued). "Importantly, since insulin sensitivity remained unchanged in NCD-fed DRF mice, we propose that dyslipidemia precedes insulin resistance in this model." (PMID 40562101, 2025). "Importantly, excess triiodothyronine impairs insulin signaling by inhibiting IRS-1 phosphorylation and PI3K/Akt activation, promoting insulin resistance." (PMID 40343070, 2025). "This increase in insulin levels suggests that, in the context of an obesogenic diet, the reduction in Cx43 expression in DVC astrocytes can potentiate the onset of metabolic syndrome symptoms, such as insulin resistance." (PMID 41227339, 2025). "Prediabetic patients typically exhibit preoperative insulin resistance, which is unlikely to improve postoperatively, whereas normoglycemic patients tend to experience a compensatory increase in insulin sensitivity after surgery." (PMID 40205383, 2025). "Our results seem to indicate that intramuscular triglyceride content in VL does not determine the development of systemic insulin resistance, nor should it be used as a marker of decreased insulin sensitivity in obesity, as previously suggested." (PMID 40566410, 2025). "Functionally, impaired insulin release driven by ABCC8 R653Q may initiate chronic postprandial hyperglycemia, which contributes to insulin resistance through downregulation of IRS1 and the PI3K–Akt pathway." (PMID 40981175, 2025). "In the context of MASLD and DM, insulin resistance does not equate to a complete shutdown of insulin signaling." (PMID 40138287, 2025). "Similarly, group-by-time interaction effects were also observed in the homeostatic model assessment of insulin resistance (HOMA-IR) and Quantitative insulin sensitivity check index (QUICKI) (P = 0.029 and P = 0.012, respectively)." (PMID 41309556, 2025). "Furthermore, DCI inhibited the activation of PKCε (i.e., a diacylglycerol-activated protein that contributes to insulin resistance) and activated the phosphoinositide-3-kinase/activates protein B [PI3K/AKT] pathway, contributing to improved insulin signaling." (PMID 40431370, 2025). "Glucose and insulin tolerance tests showed that 1-month-old Tfap2aΔHep exhibited improved glucose tolerance and insulin resistance compared to wild-type mice, but not Tfap2aΔHSC mice." (PMID 40180937, 2025). "Unfortunately, a significant indication of T2DM is the presence of insulin resistance when cells no longer effectively respond to insulin signaling, which results in hyperglycemia." (PMID 40722840, 2025). "For T2DM, UA enhances autophagic flux, mitophagy, insulin signaling, and GLUT4-mediated glucose uptake through the AMPK and PI3K/AKT pathways, reduces fasting glucose and insulin resistance in animal studies, and promotes adipose tissue browning and mitochondrial beta-oxidation." (PMID 41374004, 2025). "Over the years, various tests, including fasting plasma glucose, glycated hemoglobin A1c (HbA1c), homeostasis model assessment of insulin sensitivity (HOMA-IS) and homeostasis model assessment of insulin resistance (HOMA-IR), have been used to evaluate the effectiveness of metformin." (PMID 40775340, 2025). "Additionally, EGCG-derived autoxidation products help improve insulin sensitivity by reducing liver-derived secretory selenoprotein P (SELENOP), a protein involved in insulin resistance." (PMID 39942757, 2025). "The JAK2/STAT3 signaling pathway is involved in the development of insulin resistance in patients with T2DM, and its abnormal activation may damage pancreatic beta cells to reduce insulin synthesis." (PMID 40365304, 2025). "It should be noted that although insulin resistance is a key contributor to polycystic ovary syndrome (PCOS) in humans, and improving insulin sensitivity often alleviates PCOS symptoms, the same does not directly apply to ovarian follicular cysts (OFCs) in cattle as OFC cows are not diabetic." (PMID 40725447, 2025).
Insulin resistance (continued). "Indeed, TNF-α induces insulin resistance through mechanisms such as increased serine phosphorylation of IRS-1, which impairs insulin receptor tyrosine kinase activity and insulin signal transduction." (PMID 41574186, 2025). "Although it is well established that obesity and insulin resistance alter GLUT expression and/or trafficking in insulin-sensitive tissue, their pathophysiological effects on pulmonary glucose transport are unknown." (PMID 41295303, 2025). "Pancreata from human subjects with insulin resistance showed a 2–3-fold increase in insulin/glucagon bi-hormonal cells compared with individuals without insulin resistance, especially within larger islets." (PMID 39791735, 2025). "Insulin resistance occurs when blood glucose uptake fails to respond to insulin signaling, resulting in reduced insulin responsiveness compared with normal stimulation." (PMID 39873298, 2025). "We assume that, with falling IR, this reflects changes in insulin sensitivity assumed to be due to placental aging and a fall in hormone production, but a direct measurement of insulin resistance is not usually possible." (PMID 41227133, 2025). "Similarly, a 70% ethanol extract of MO leaves (MO 400) reduced body weight, adiposity, glucose, insulin, and HOMA-IR (homeostatic model assessment for insulin resistance) while increasing insulin sensitivity." (PMID 40149610, 2025). "An improvement in the first phase of insulin secretion and an increase in hepatic sensitivity to insulin were observed, but without changes in peripheral insulin resistance." (PMID 40902424, 2025). "For example, lower insulin secretion and lower insulin resistance have been reported in alcohol drinkers than in nondrinkers." (PMID 41041632, 2025). "Insulin resistance, as assessed by insulin tolerance testing, remained without significant differences in both groups throughout the study time points." (PMID 41348832, 2025). "Even after diagnosis, autoantibody-positive people initially diagnosed with T2D not requiring insulin treatment exhibited hyperglycemia in the presence of insulin resistance and partly reserved β-cell function." (PMID 39998445, 2025). "TNF-α induces insulin resistance through direct negative interference with the insulin signaling pathway, IRS1 phosphorylation, and alteration of adipocyte differentiation and metabolism." (PMID 41226064, 2025). "Serum insulin levels and HOMA-IR index were also significantly increased in the HS group, which is significantly higher than the normal range, indicating the occurrence of insulin resistance." (PMID 40070461, 2025). "Altered insulin/insulin growth factor signaling has the potential to slow aging without the complications of insulin resistance by modulating methionine cycle dynamics." (PMID 40093182, 2025). "Based on these data, the TyG index is a useful indicator of insulin resistance even in patients with reduced insulin secretory ability because it does not use insulin as a variable." (PMID 40507147, 2025). "Insulin resistance is defined as an inadequate response to insulin in tissues (adipose, skeletal muscle), central nervous system, and liver, being one of the major factors leading to hyperglycemia and T2DM, along with impaired insulin secretion." (PMID 41346429, 2025). "NAS correlated with the acute insulin response to glucose (AIRg) (r = 0.68, P = 0.005), suggestive of a correlation between insulin resistance and NAS; however, NAS did not correlate with the homeostatic model assessment for insulin resistance." (PMID 40272888, 2025). "Insulin resistance occurs when the body’s cells do not respond properly to insulin, leading to elevated blood sugar levels." (PMID 39859479, 2025). "In hepatic metabolic regulation, PGE2 from Kupffer cells may affect liver insulin resistance by disrupting SOCS3, which decreases insulin-driven glucose use." (PMID 40969371, 2025).
Insulin resistance (continued). "The aim of present study was to understand the mechanism of how prolonged exposure of physiological levels of insulin in the absence of glucose stimulus‐induced insulin resistance." (PMID 39471069, 2025). "The Metabolic Score for Insulin Resistance (METS-IR) Index is a recently devised indicator that exhibits a stronger correlation with HEC compared to other IR indices not based on insulin." (PMID 40421238, 2025). "Insulin sensitivity should be considered when studying Beta cell functionality with insulin secretion knowing that, if insulin resistance increases, Beta cells will compensate by secreting more insulin without reflecting Beta cell health." (PMID 40943107, 2025). "CJE can significantly improve glucose tolerance and insulin sensitivity in T2DM mice by reducing liver lipid accumulation, promoting the regeneration and recovery of islet β-cells, reducing insulin resistance, and thus ameliorating glucose and lipid metabolism disturbances in T2DM mice." (PMID 40077469, 2025). "Fenofibrate reduced triglycerides, non-HDL cholesterol, insulin levels, and insulin resistance index in MetS animals, whilst promoting an antioxidant environment." (PMID 41007642, 2025). "We showed that PFKFB2 is labile and the enzyme is rapidly degraded in the absence of insulin signaling, and thus becomes chronically decreased in a type 1 diabetes model and with insulin resistance." (PMID 40310487, 2025). "Elevated cytosolic acetyl-CoA enhances global protein acetylation, suppressing fatty-acid oxidation; persistent hyperglycemia increases O-GlcNAcylation of key signaling proteins, desensitizing insulin pathways; and aberrant phosphorylation of IRS and AKT further amplifies insulin resistance." (PMID 41373704, 2025). "In the case of insulin resistance, insulin is not effective as the body is not using it properly, so insulin production rises to maintain glucose homeostasis." (PMID 41404215, 2025). "In insulin-resistant H9C2 cardiomyocytes, berberine promoted AMPK phosphorylation, elevated GLUT4 protein levels, and enhanced glucose uptake, further alleviating insulin resistance." (PMID 41471379, 2025). "There was not significant difference in FBG, plasma insulin and homeostasis model assessment of insulin resistance (HOMA-IR) levels between C57 and APP/PS1 control mice." (PMID 40341393, 2025). "Further group comparisons revealed that insulin resistance alone reduced extracellular leucine and valine, which was not consistently observed in insulin-resistant cells that also received Dex." (PMID 40422898, 2025). "Glucose, insulin, homeostatic model assessment for insulin resistance (HOMA-IR), and hepatic lipid accumulation were assessed at the end of the 8-week intervention as markers of whole-body insulin resistance." (PMID 40048260, 2025). "Of note, we did not measure insulin in the current studies, but adiposity is known to be the strongest predictor of insulin resistance in children." (PMID 41306439, 2025). "Since HOMA-IR is calculated from fasting insulin and glucose levels, it effectively reflects insulin resistance differences between diabetic and non-diabetic states independent of postprandial influences." (PMID 40509433, 2025). "In patients with obesity, the effect of VLCKD is powerful in reducing plasma insulin levels; consequently, HOMA-IR and HOMA-beta, which represent markers of insulin resistance and beta-cell function, respectively, display significant improvements after this dietetic intervention." (PMID 38778593, 2025). "As fasting blood glucose and insulin levels improved, HOMA-IR index in AE-treated groups, however, remained high and was not significantly different from DC group, further suggesting persistent insulin resistance." (PMID 40448078, 2025). "Many studies proposed younger age, shorter duration of DM, lower HbA1c, no preoperative insulin use found a higher rate of complete remission with lower insulin resistance." (PMID 40434569, 2025).
Insulin resistance (continued). "Elevated insulin levels without concurrent insulin resistance have been observed in lean PCOS patients and animal models." (PMID 40013621, 2025). "Wang’s study demonstrated that a high dose of P. sibiricum polysaccharide (PSP) significantly reduced body weight, FBG, fasting insulin (FINS), homeostasis model assessment-insulin resistance (HOMA-IR), and other parameters in STZ-induced diabetic rats (P < 0.05)." (PMID 41001671, 2025). "Genes involved in lipid synthesis and oxidation, such as SREBP1 or ACC1, were found to be up-regulated in GCs from women with PCOS and insulin resistance, as opposed to non-insulin-resistant women with PCOS, potentially leading to excessive ROS production." (PMID 40723795, 2025). "When patient has Genetically similar to obese nondiabetic rats, diabetic rats develop insulin resistance, impaired fatty acid metabolism, and defective glucose-stimulated insulin secretion." (PMID 41190158, 2025). "Mechanistically, these improvements in insulin sensitivity are attributed to resveratrol’s activation of AMPK, suppression of inflammation, and enhanced mitochondrial function, all of which counteract insulin resistance." (PMID 40563357, 2025). "In the present investigation, DEX injection induced insulin resistance, as evidenced by hyperglycemia, hyperinsulinemia, elevated HOMA-IR index, hypercholesterolaemia, hypertriglyceridemia, diminished insulin sensitivity index, and reduced GLUT4 expression in skeletal muscles." (PMID 40541990, 2025). "Excess body fat, particularly abdominal fat, is a major contributor to insulin resistance; therefore, GLP-1 receptor agonists might help increase the body’s sensitivity to insulin, potentially mitigating or even reversing the effects of insulin resistance." (PMID 40725728, 2025). "Transcriptomic data show that insulin secretion‐related genes (IRS1, PRKCA/PKCα) in cave loaches are significantly downregulated, rather than exhibiting mutations related to insulin resistance." (PMID 41383212, 2025). "Therefore, these components are important to improve insulin sensitivity and decrease systemic insulin levels which directly mitigate one of the most important drivers of MAFLD; insulin resistance." (PMID 40444252, 2025). "Under high-glucose and insulin conditions, DHM significantly increases glucose consumption and intracellular glycogen synthesis, indicating its potential therapeutic effect in improving insulin resistance." (PMID 40740995, 2025). "Subjects with obesity and insulin resistance had significantly higher fasting plasma glucose, insulinemia, glucagon, and GLP-1 levels and similar fasting GIP values compared with those with obesity and normal insulin sensitivity." (PMID 40649920, 2025). "The treatment improved insulin secretion capacity (HOMA-β) and insulin resistance (HOMA-IR)." (PMID 41378215, 2025). "Furthermore, this group had higher insulin resistance (Homeostatic Model Assessment of Insulin Resistance [HOMA-IR], P < .001) and lower insulin sensitivity (QUICKI, P < .001)." (PMID 39833091, 2025). "Group D exhibited the highest insulin resistance (median HOMA-IR = 3.47, QUICKI = 0.32, insulin = 15.32 μIU/mL), followed by Group C (HOMA-IR = 2.65, QUICKI = 0.33, insulin = 11.39 μIU/mL), indicating severe metabolic dysregulation in phenotypes with ovulatory dysfunction and polycystic ovaries." (PMID 41220482, 2025). "A higher dose (at least above 25 g/day) intake of EVOO with an average duration of above 8 weeks significantly decreased insulin (SMD = −0.28, 95% CI: −0.51, −0.05) and homeostatic model assessment for insulin resistance (HOMA‐IR) (SMD = −0.19, 95% CI: −0.35, −0.03)." (PMID 41142012, 2025). "Volatile anaesthetics impair insulin signalling, inhibit insulin secretion by opening KATP channels in β cells of the pancreas, and induce hepatic insulin resistance rapidly, which may promote more severe hyperglycaemia compared with TIVA." (PMID 40511259, 2025).
Insulin resistance (continued). "RAW264.7 macrophage-conditioned media also induced damage and insulin resistance in SH-SY5Y cells, though the latter was significantly milder than that seen in the BV2 model and could be rescued with insulin." (PMID 40724831, 2025). "A study investigating American adults found that higher DII scores correlated with increased fasting plasma glucose, fasting serum insulin, and homeostatic model assessment of insulin resistance (HOMA-IR) scores, indicating a greater odds of prediabetes and insulin resistance." (PMID 41170355, 2025). "It has been shown that there is an increased SOCS-1 expression in insulin-sensitive tissues in obesity and that this inhibits the phosphorylation of IRS-1 and IRS-2, leading to the inhibition of downstream signaling and insulin resistance." (PMID 40572705, 2025). "This study suggested that QHTTF treatment may regulate insulin resistance by upregulating IRS-1 and GLUT4 expression in pancreatic tissues, potentially indicating modulation of the insulin signaling pathway." (PMID 41011216, 2025). "Data regarding serum insulin levels are consistent with blood glucose levels, indicating that the increased insulin resistance developing in response to high fructose diet was not corrected by either HD or LD Enalapril treatment." (PMID 40149735, 2025). "Terazosin treatment did not enhance glucose intolerance and insulin resistance in GPR119−/− mice, lower fasting blood glucose and serum insulin levels, or alleviate weight loss." (PMID 39413003, 2025). "Insulin resistance (IR) refers to a state in which insulin-sensitive tissues do not respond to insulin adequately." (PMID 39861104, 2025). "It has been reported that insulin action, as measured by the euglycemic insulin clamp, decreases with age in Europeans, but that the age-related increase in insulin resistance is no longer statistically significant after adjustment for BMI." (PMID 40002793, 2025). "The insulin resistance phenotype was explained by defects in insulin signaling and not by total abundance of the insulin-responsive glucose transporter, GLUT4." (PMID 40328250, 2025). "To further assess the effects of Nok on these parameters in db/db diabetic mice, we conducted oral glucose tolerance tests (OGTT) and insulin tolerance tests (ITT), alongside measurements of serum insulin levels and calculation of the Homeostatic Model Assessment of Insulin Resistance (HOMA-IR)." (PMID 40430283, 2025). "In fact, HP-EVOO improved insulin sensitivity in obese rats on an HFD, as manifested by a decrease in the insulin resistance index and the homeostatic model assessment for insulin resistance (HOMA-IR) and an increase in activity of the insulin degrading enzyme (IDE) in the liver." (PMID 40136590, 2025). "In 50 non-diabetic humans, serum level of 15-keto-PGE2 was inversely correlated with the Homeostasis Model Assessment of Insulin resistance (HOMA-IR) index (r = −0.37, P = 0.007), fasting glucose (r = −0.31, P = 0.02), and fasting insulin (r = −0.33, P = 0.02)." (PMID 40119175, 2025). "Furthermore, NAC’s potent antioxidant activity has been found to interfere with insulin signaling by reducing insulin-induced H2O2 formation, which is required for proper insulin receptor activation, as NAC can contribute to insulin resistance." (PMID 40076537, 2025). "Indeed, the first large-scale genetic analyses have unexpectedly implicated glycaemic metabolism, through various parameters such as insulin resistance (HOMA-IR), fasting insulin, beta-cell function, and fasting glucose." (PMID 41402238, 2025). "Grip strength, skeletal muscle mass (SM), skeletal muscle mass index (SMI), 6‐m gait speed (6‐m GS), glycated haemoglobin (HbA1c), fasting blood glucose (FBG), fasting insulin (FINS) and homeostasis model assessment of insulin resistance (HOMA‐IR) were measured at 0, 3 and 6 months, respectively." (PMID 40464168, 2025).